TEPSIN (TEPSIN adaptor related protein complex 4 accessory protein)
Description:
Associates with the adapter-like complex 4 (AP-4) and may therefore play a role in vesicular trafficking of proteins at the trans-Golgi network.
Synonyms: C17orf56; ENTHD2; FLJ31528
Tractability: Antibody: UniProt places it where antibodies can reach, with high confidence. PROTAC: ubiquitination databases record sites on it.
Gene: Protein-coding gene on chromosome 17 (81,228,277 to 81,239,091, reverse strand). Ensembl gene ENSG00000167302.
Subcellular location: Golgi apparatus, trans-Golgi network membrane; Cytoplasmic vesicle; Cytoplasm, cytosol
Subcellular location (Human Protein Atlas): Vesicles
Gene Ontology:
Molecular function: protein binding; protein-containing complex binding
Cellular component: coated vesicle membrane; cytoplasm; cytoplasmic vesicle; organelle membrane; trans-Golgi network membrane; cytosol; Golgi apparatus
Genetic constraint (gnomAD): Loss-of-function variants: 51 observed, 42.79 expected, observed/expected ratio (o/e) 1.19, 90% interval 0.95 to 1.5. The synonymous counts are far from expectation, so gnomAD's model fits this gene poorly and the ratio says little. Missense variants: 838 observed, 751.15 expected, observed/expected ratio (o/e) 1.12, 90% interval 1.05 to 1.18. Synonymous variants: 392 observed, 320.74 expected, observed/expected ratio (o/e) 1.22, 90% interval 1.12 to 1.33.
Homologues: Orthologues: chimpanzee TEPSIN (98% identical), macaque TEPSIN (95% identical), pig TEPSIN (73% identical), rat Tepsin (71% identical), mouse Tepsin (70% identical), guinea pig TEPSIN (69% identical), dog TEPSIN (69% identical), tropical clawed frog tepsin (44% identical), zebrafish tepsin (40% identical).
Diseases named in the same sentence as TEPSIN in open-access papers:
TEPSIN is named in the same sentence as 2 diseases in open-access papers, as found by Europe PMC text mining. Sharing a sentence is not in itself a finding about the gene and the disease. The quoted sentences say what the papers report.
embryonal carcinoma (1 paper, 2022). A non-seminomatous malignant germ cell tumor characterized by the presence of large germ cells with abundant cytoplasm resembling epithelial cells, geographic necrosis, high mitotic activity, and pseudoglandular and pseudopapillary structures formation. "Less reported about its splicing role, we found that the PSI value of TEPSIN was significantly up-regulated in embryonal carcinoma and NCCIT cells." (PMID 36713456, 2022).
prostate carcinoma (1 paper, 2022). A carcinoma that arises from epithelial cells of the prostate gland. "TEPSIN Adaptor Related Protein Complex 4 Accessory Protein (TEPSIN) is a membrane serine protease expressed in a variety of human tissues including kidney, prostate and thyroid, precise control of Hepsin proteolytic activity is an effective treatment for prostate cancer." (PMID 36713456, 2022).